WT1 (WT1 transcription factor)
Diseases named in the same sentence as WT1 in open-access papers (continued):
Sharing a sentence is not in itself a finding about the gene and the disease.
leukemia (continued). "Studies have shown that WT1 is often regarded as an oncogene in leukemia." (PMID 38062912, 2023). "For example, leukemias characterized by high WT1 mRNA and protein levels in leukemic blast cells tend to correlate with a notably worse prognosis, indicating an oncogenic role of WT1 in these leukemic cells." (PMID 37765274, 2023). "WT1 is closely related to the occurrence, development, and prognosis of leukemia." (PMID 38293695, 2023). "In the present study, we sought to solve some of these issues by offering a directory of lymphoma and leukemia cell lines, well characterized for expression of WT1 mRNA and protein and extensively screened for WT1 alterations across its entire coding and splicing regions." (PMID 37444601, 2023). "Therefore, the two contradictory roles of WT1 in leukemia, i.e., being an oncogene when aberrantly expressed and a tumor suppressor gene when mutated, has made this gene a subject for numerous research projects." (PMID 37444601, 2023). "Evidence has shown that high WT1 expression in leukemia may contribute to the maintenance of malignant phenotypes via various molecular mechanisms." (PMID 37765274, 2023). "In leukemia and various types of solid tumors, high expression of WT1 is often observed." (PMID 37765274, 2023). "Promising strategy by T cell receptor gene therapy targeting WT1 seemingly could prevent leukemia relapse in AML patients after transplantation." (PMID 36824620, 2022). "Studies has confirmed that overexpressed BAG3 could reverse the pro-apoptotic effect of WT1 silencing and regulate the leukemia stem cell-supporting activity." (PMID 36727051, 2022). "Many studies have shown that WT1 is highly expressed in human leukemia cells." (PMID 35915803, 2022). "It has been demonstrated that naked heptamer-type sgRNAs targeting the WT1 mRNA can reduce its mRNA levels and WT1 protein amounts in the WT1-expressing leukemia cells and that these sgRNAs efficiently induce apoptosis in these cells but not in WT1-nonexpressing cells." (PMID 35628198, 2022). "Our object is to find a WT1 inhibitor to restore leukemia cell differentiation." (PMID 36500358, 2022). "In a mouse leukemia model, shikonin could decrease the WT1 protein to prevent leukemia development in a dose-dependent manner." (PMID 36500358, 2022). "Therefore, this study aims to observe the differentiating effect of shikonin on Wilms’ tumor 1 (WT1)-positive HL-60 cells and investigate the fate of the differentiated leukemia cells." (PMID 36500358, 2022). "Thus, we also decided to generate Wt1-overexpressing subclones to establish our immune-competent leukemia MRD mouse model." (PMID 35486629, 2022). "Adding leukemia-associated antigens (e.g., WT1 and PRAME) to cultures with/without the cultivation of cells can help to detect/enrich low frequencies of specific cells." (PMID 36613907, 2022). "Kinetics of CMV-CTL and WT1-CTL after transplantation might be associated with measurable residual disease and later leukemia relapse." (PMID 36824620, 2022). "To explore whether shikonin can inhibit WT1 to restore leukemia cell differentiation, we use molecular docking and DARTS to verify the binding of shikonin to the WT1 protein." (PMID 36500358, 2022). "Wilms tumor protein (WT1) is a zinc-finger transcription factor that is selectively overexpressed in leukemia and other types of cancers, and it has been suggested that several WT1-derived peptides could be used as a vaccine." (PMID 36017166, 2022). "Because immunotherapy should preferably be started in patients with a relatively low leukemia burden, WT1-directed immunotherapy may help to clear MRD more promptly and effectively." (PMID 33740924, 2021). "It has been reported that WT1 appears to have a growth regulatory role in many solid cancers including lung, colon, pancreatic, breast, and gastric, as well as in leukemia and lymphoma." (PMID 34845427, 2021). "qRT-PCR indicated successful silencing of wt1 in MLL-AF9-induced murine leukemia." (PMID 32580769, 2020).
leukemia (continued). "Furthermore, WT1 silencing by shRNA resulted in an increased proportion of cells in the G0/G1 phase and a reduced proportion of cells in the S phase in these leukemia cells." (PMID 33110919, 2020). "WT1 expression encompasses both hematopoietic and solid tumors and therefore, a TCRm targeting this oncoprotein should have a broad application as a therapeutic agent against a variety of human leukemias, myeloma and solid tumors." (PMID 33569049, 2020). "Furthermore, it raises the possibility of WT1 expression as the marker for topical leukemia relapse." (PMID 31977890, 2020). "However, overexpression of WT1 has been detected in several types of malignancy including some types of leukemia." (PMID 33110919, 2020). "To address these issues, we developed a strategy in which cytotoxic T lymphocytes (CTLs) are regenerated from iPSCs that were originally derived from T cells and succeeded in regenerating CTLs specific for the WT1 antigen, which exhibited therapeutic efficacy in a xenograft model of leukemia." (PMID 32259478, 2020). "Besides the leukemia model, effects of WT1 silencing on the malignant phenotype of other tumor cells supported the oncogenic role of WT1." (PMID 33110919, 2020). "Loss of WT1 impaired self-renewal ability in LSC and delayed the progression of leukemia." (PMID 32580769, 2020). "Our finding confirmed that WT1 plays an oncogenic role in the leukemia cells." (PMID 33110919, 2020). "Successfully, both WT1 RNA and protein levels were downregulated in the leukemia cells." (PMID 33110919, 2020). "For example, TCR-like antibodies have been conjugated with fluorescent reagents to detect the expression level of the Wilms tumor 1 (WT1) RMFPNAPYL peptide/human leukocyte antigen (HLA)-A2 complex on the leukemia cell surface, which offers a clear map of the tumor-specific antigen profile." (PMID 31521180, 2019). "Functional studies will be performed to confirm their anti-CML cytotoxicity by producing TCR gene-modified T cells, it may be possible to provide a new TCR-T cell clone for WT1 + leukemia and maybe for WT1 + solid tumors immunotherapy." (PMID 31223481, 2019). "While several leukemia-associated antigens (LAA) have been identified (such as WT1, Cyclin A1), leukemia specific antigens (LSA) have not been as well defined." (PMID 31291378, 2019). "A recent report indicated that a member of EGR family, WT1 (Wilms tumor suppressor gene 1) may recruit TET2 to demethylate its binding sites in leukemia cells." (PMID 31467272, 2019). "We previously treated hematopoietic malignancies including leukemia and various kinds of solid tumors with WT1 HLA class I peptide vaccine and reported that the vaccination elicited WT1-specific immunological response, followed by clinical responses without severe adverse effects." (PMID 30430205, 2019). "The top 10 articles covered the updating of treatments for childhood leukemia, different mechanisms of immunotherapy, WT1 targeted therapy, a case series report, and a clinical study." (PMID 31611792, 2019). "WT1 is aberrantly overexpressed in leukemia and lymphoma cells." (PMID 31628525, 2019). "Therefore, we tested for a potential impact of RGFP966 on the leukemia- and stemness-associated transcription factors β-catenin, MYC, and WT1." (PMID 31561534, 2019). "However, it was subsequently revealed that WT1 acts as an oncogene in leukemia, lung cancer, breast cancer, and glioblastoma." (PMID 29016617, 2017). "Upon forced overexpression, the WT1 protein interferes with differentiation of myeloid cell lines and cooperates with the fusion protein RUNX1/RUNX1T1 (AML1/ETO) in a rapid induction of leukemia in transgenic mice, clearly demonstrating a leukemogenic role for WT1." (PMID 29152069, 2017). "However, subsequent accumulating studies demonstrated that high expression of WT1 was detected in different types of solid cancers and hematological malignancies, such as breast cancer, lung cancer, and leukemia." (PMID 27821145, 2016).
leukemia (continued). "This novel mechanistic knowledge of how mammea E/BB affects WT1 transcriptional function in leukemic cells may be useful in the future development of the natural product for therapeutic treatment of leukemia patients." (PMID 27193767, 2016). "Wilms’ tumor 1 (WT1) is a biological marker for predicting leukemia progression." (PMID 27193767, 2016). "Moreover, expression of the WT1 gene and its product has been used as biological markers for diagnosis and evaluation of the prognosis in leukemia and minimal residual disease (MRD)." (PMID 27193767, 2016). "The upregulation of WT1 is present in all leukemia subtypes." (PMID 27275197, 2015). "However, it was reported that the wild-type WT1 gene is overexpressed in leukemia and various kinds of solid cancers including lung, colon and pancreatic cancers." (PMID 26090994, 2015). "We therefore hypothesized that despite our findings with breast cancer, CpG island methylation may play a role in regulating WT1 expression in leukemia, since WT1 is expressed in hematopoietic stem/progenitor cells under tight developmental control." (PMID 25794157, 2015). "We therefore investigated whether expression of WT1 lncRNA (the antisense-oriented noncoding RNA) correlates with the methylation status of the Intron 1 CpG island in human leukemia cells." (PMID 25794157, 2015). "Furthermore, IFN-β enhanced tumor immunity in a vaccine model for leukemia through induction of WT1-specific cytotoxic T cells and enhancement of NK cell activity." (PMID 26441059, 2015). "To determine whether WT1 is upregulated by hypoxia in leukemia cells as well, we grew U937 cells for 48 hours in 1% O2 and compared WT1 mRNA expression with U937 and K562 cells grown under atmospheric conditions." (PMID 25794157, 2015). "Thus, in these 3 human leukemia cell lines, the methylation status of the Intron 1 CpG island correlates with WT1 mRNA expression." (PMID 25794157, 2015). "Previously, we have reported that sgRNA can be easily taken up by cultured cells without any transfection reagents, and naked sgRNAs targeting Bcl2 or WT1 mRNA can reduce their mRNA level and the amount of protein as well as inducing apoptosis in leukemia cells." (PMID 25437003, 2014). "High expression of the WT1 gene in solid cancers and leukemia suggested that the WT1 protein might be a possible tumor-associated antigen." (PMID 25026998, 2014). "Thus, WT-1 represents an attractive immunotherapeutic target, and there are currently 3 open clinical trials for adult leukemia patients that center around this unique antigen." (PMID 26056592, 2014). "Nevertheless, several TCR constructs derived from conventional, human T-cells with physiologic avidities have undergone extensive preclinical testing and will now be studied in human leukemia trials including those that redirect T-cells against HLA-A2 restricted epitopes of HA-1 and WT-1." (PMID 26056592, 2014). "However, concern still remains about adverse events resulting from damage to normal tissues mediated by cytotoxic T lymphocytes (CTLs), since WT1 is also expressed in some lineages of normal cell as well as leukemia cells." (PMID 24393438, 2014). "In contrast, WT1 was found to be overexpressed in leukaemia." (PMID 23484026, 2013). "Indeed, type I mutations are common in NUP98 rearranged leukemia, including mutations in the NRAS, KRAS, KIT, WT1 and FLT3 genes." (PMID 23332017, 2013). "While the treatment of leukemia-bearing NOD/SCID mice with T cells modified with a WT1-specific TCR eliminated leukemia cells in the bone marrow of most mice, treatment with T cells transduced with a TCR with irrelevant specificity did not diminish the leukemia burden." (PMID 23241263, 2012). "Ndrg2 expression is induced by WT1, a transcriptional regulator frequently expressed in leukemias." (PMID 20098702, 2010). "Moreover, clinical trials using peptide vaccines against WT1 in patients with leukemia, breast, and lung cancer are showing promising therapeutic effects." (PMID 20122399, 2010).
leukemia (continued). "These regions of UPD seemed to be non-random and may be used to unmask pre-existing recessive mutations in leukemia genes, such as CEBPA, WT1, FLT3 and RUNX1." (PMID 18221515, 2008). "All these reports have demonstrated that WT1 proteins or peptides could be used as molecular targets for the development of specific cell based anti-leukemia therapy." (PMID 19662212, 2007). "In recent years, it has been found that WT1 could be used as a molecular marker to generate specific cytotoxic T cells (CTL) against leukemia cells." (PMID 19662212, 2007). "Although the sequence of the WT1 mRNA was not examined in the current study, it is likely that the WT1 gene related to leukemia to be a wild type rather than mutation." (PMID 19662212, 2007). "This suggests that shogaol may possibly target other leukemia-related proteins apart from WT1." (PMID 40022126, 2025). "Consequently, WT1 emerges as a desirable objective for CTL stimulation in leukemia immunotherapy." (PMID 39411712, 2024). "An additional consideration is that the ddPCR test could also yield a false negative test, either from lack of TAA expression within the leukemia, or a mutation within the gene target, as has been reported with WT1 in certain acute leukemias." (PMID 36248870, 2022). "Therefore, we speculated that the WT1 gene may be a key target for regulating leukemia cell differentiation." (PMID 36500358, 2022). "Nevertheless, because WT1 is not a leukemia specific marker, patients receiving WT1-directed IFN-α therapy may be at risk of overtreatment." (PMID 35154096, 2022). "To determine if these tumor antigens could be simultaneously detected and discriminated for quantitation, we used cancer cell lines known to express the three TAA: hepatoblastoma (HEP3B), which expresses BIRC5; and K562, an immortalized leukemia line that expresses WT1 and PRAME." (PMID 36248870, 2022). "In addition, we observed that patients with WT1+ alone had a trend of a lower CIR than those with MRDco+ (i.e., WT1+ and MFC+), which suggested that there might be a lower leukemia burden for patients with WT1+ alone." (PMID 33740924, 2021). "Functional and molecular studies to identify the effect of WT1 silencing on key cellular functions in this work showed that downregulation of WT1 expression resulted in dramatic growth inhibition, enhanced apoptosis, and S phase progression inhibition in K562 leukemia cells." (PMID 33110919, 2020). "Additionally, overexpression of WT1 sustains the survival of leukemia blasts." (PMID 32580769, 2020). "However, whether WT1 is enriched in the leukemia-initiating cells (LICs) and leukemia stem cells (LSCs) and facilitates the self-renewal of LSCs remains poorly understood." (PMID 32580769, 2020). "However, the types of leukemia associated-antigens in AML patients are relatively complex, thus not allowing a clear definition of the types of antigens recognized by clonally expanded TCR Vβ T cells after injection with a WT1 vaccine." (PMID 31223481, 2019). "Thus, WT1 is an attractive target for inducing CTLs against leukemia for immunotherapy." (PMID 30622438, 2019). "Although WT1 is overexpressed in the majority of leukemias and can be used as a marker for minimal residual disease and maybe even vaccination attempts, the prognostic and therapeutic relevance of high or absent WT1 expression levels is not unequivocally accepted." (PMID 31467532, 2019). "Regarding the entire group, PB WT1-mRNA expression was associated with prognosis, as those patients showing WT1-mRNA overexpression had higher risk for disease progression and AML transformation and accordingly shorter progression-free, leukemia-free and overall survival in univariate analysis." (PMID 31719523, 2019).
leukemia (continued). "Interestingly, the authors documented that the addition of nivolumab to CTL cultures for several days increased both specific T-cell responses against various leukemia-associated antigens, mainly PRAME, RHAMM and WT1, as well as T cell cytotoxic effects against primary AML blasts." (PMID 30783516, 2019). "The findings of this study will contribute to the development of strategies for generating sufficient quantities of WT1 leukemia-specific T cells from healthy donors to augment effective T-cell immunity in leukemia patients and to broaden the applicability of T-cell-based therapies for leukemia." (PMID 30678050, 2019). "Additionally, WT1 peptide-based immunotherapy shows good clinical responses, such as reduction in tumor sizes, demonstrating that WT1 vaccination should be a promising treatment for patients with lung cancer, breast cancer, and leukemia." (PMID 27821145, 2016). "In addition, our molecular data are suggestive of a regulatory loop in which WT1, by repressing the expression of ZNF224 gene, could prevent the proapoptotic effect of the ZNF224-WT1 complex itself, thus contributing to the WT1 pro-survival role in leukemia." (PMID 26320177, 2015). "It is known that AML cells express leukemia-associated antigens (LAA) that can be recognized by the immune system, including those derived from proteins such as proteinase 3 (PR3), receptor for hyaluronic acid-mediated motility (RHAMM), and Wilm’s tumor-1 (WT1), among others." (PMID 25914882, 2015). "Despite the plethora of research on the role of WT1 in leukemia, it remains unclear if the abundant WT1 levels represent ectopic expression during carcinogenesis or simply reflects the arrested differentiation during early hematopoiesis, since most AML have an immature phenotype." (PMID 24405639, 2014). "It is also possible that other molecular aberrations, e.g., MiR-15a/16-1, which is as a tumor suppressor that down-regulates WT1 expression in the process of leukemia cell proliferation, could be another contributing factor to the observed differences in the WT1 overexpression." (PMID 24667279, 2014). "However, subsequent research has revealed that WT1 may function as an oncogene in other types of cancers including leukaemia and breast cancer." (PMID 23484026, 2013). "In summary, our innovative computational model enables the identification of WT1-specific T-cells from clinical TCR sequencing datasets and facilitates the large-scale monitoring of leukemia-antigen-specific immune responses." (PMID 40847198, 2025). "In conclusion, our novel computational models enable large-scale WT1-specific T-cell identification from TCR sequencing datasets and leukemia-antigen-specific immune response monitoring." (PMID 40847198, 2025). "Despite these findings, the anti-leukemia mechanisms of G. pentaphyllum in relation to the leukemia cell proliferation markers FLT3 and WT1 remain unexplored." (PMID 40361130, 2025). "This study investigates the anti-leukemia activities of active G. pentaphyllum leaf extracts and their components, focusing on the inhibition of FLT3 and WT1 activity." (PMID 40361130, 2025). "WT1 is also involved in the carcinogenic process and is overexpressed in MPM, leukemia, and various solid tumors." (PMID 39116074, 2024). "WT1, with an oncogenic role in hematopoietic progenitor cells, is a tumor marker that is expressed specifically in MDS and leukemia cells." (PMID 39087180, 2024). "Cesaro concluded that WT1 enhances expression of BAG3, which contributes to the prosurvival role of WT1 in leukemia." (PMID 36980278, 2023). "In this case, Wilm’s tumor protein (WT1) ligands, an upregulated protein in many human leukemias and cancers, were covalently attached onto solubilized SWCNT scaffolds to form SWCNT–peptide constructs." (PMID 37047572, 2023). "Wilms Tumor 1 (WT1): WT1 is a transcription factor up-regulated in a wide variety of malignancies, including solid tumors, lymphomas, and leukemias." (PMID 37345057, 2023).